SRF (serum response factor)
Diseases named in the same sentence as SRF in open-access papers (continued):
Sharing a sentence is not in itself a finding about the gene and the disease.
Hypoglycemia (1 paper, 2025). A decreased concentration of glucose in the blood. "Furthermore, restoring glucose reverses neurodegenerative changes caused by hypoglycemia, with a gradual decrease in SRF/MRTF-A transcriptional activity, highlighting a strong potential for neuronal recovery." (PMID 41408035, 2025). "The activation of SRF/MRTF-A represented a neuron-specific adaptive response to hypoglycemia in both in vitro and in vivo models." (PMID 41408035, 2025). "Collectively, our results revealed a neuron-intrinsic mechanism linking glucose deprivation to reversible neurodegeneration via SRF/MRTF-A, offering potential targets for preventing hypoglycemia-associated brain damage." (PMID 41408035, 2025). "In summary, we showed that hypoglycemia activates SRF/MRTF-A-mediated neurodegenerative pathways in in vitro and in vivo models." (PMID 41408035, 2025). "SRF was consistently and significantly enriched by glucose starvation at 24 and 48 h, suggesting its involvement in the cellular responses to hypoglycemia." (PMID 41408035, 2025). "Collectively, these findings demonstrate that SRF/MRTF-A is a central mediator of the neuronal response to glucose deprivation, contributing to hypoglycemia-induced neurodegeneration." (PMID 41408035, 2025). "Therefore, pharmacological inhibition of SRF and MRTF-A presents a promising therapeutic approach for preventing hypoglycemia-induced neurodegeneration and AD-like pathology." (PMID 41408035, 2025). "In contrast, astrocytes maintain viability during hypoglycemia despite low SRF and MRTF-A levels, suggesting an alternative survival mechanism, whereas microglia lacking SRF/MRTF-A activity fail to utilize ECM resources, which reduces their survival under glucose-depleted conditions." (PMID 41408035, 2025).
Immunodeficiency (1 paper, 2022). Failure of the immune system to protect the body adequately from infection, due to the absence or insufficiency of some component process or substance. "There are numerous reports on integrin-mediated functions being inhibited in SRF or MRTF-A deficient cells and that MRTF-A loss-of-function mutations lead to severe immunodeficiency." (PMID 36238292, 2022).
Insulin resistance (1 paper, 2010). Increased resistance towards insulin, that is, diminished effectiveness of insulin in reducing blood glucose levels. "We hypothesize that some transcriptional pathways identified in the current analysis, including CREB, NRF-1 and SRF, may be additional novel molecular mediators of the transcriptomic phenotype associated with insulin resistance, and thus potential targets for future intervention strategies." (PMID 20369014, 2010).
insulinoma (1 paper, 2019). "Small interfering RNA-mediated reduction of SRF in a rat insulinoma cell line partially inhibited the ability of these cells to respond to glucose." (PMID 30987204, 2019).
liver cirrhosis (1 paper, 2017). "Our results regarding the pathway of AMPK-mediated suppression of SRF and HSC activity support such beneficial effects of metformin on patients with liver cirrhosis." (PMID 29029395, 2017).
lung disease (1 paper, 2025). "Analysis of Egr1 revealed upstream control by SRF, ELK1, and CREB, all of which are involved in activity-dependent gene expression, lung disease and response to infection." (PMID 40831503, 2025).
lupus nephritis (1 paper, 2026). Glomerulonephritis in the context of systemic lupus erythematosus. "Interestingly, PALLD was strongly correlated with MKL1, MKL2, and SRF in human lupus nephritis samples." (PMID 41131992, 2026). "In lupus nephritis, MKL1, MKL2, and SRF also negatively correlated with GFR, and PALLD was shown to negatively correlate with GFR." (PMID 41131992, 2026).
lymphoid cancer (1 paper, 2012). "However, transcription of cytoskeletal regulators like MYH9 and MYL9 is elevated in different non-lymphoid cancer cell lines, which depend on MRTFs and SRF for cell spreading, adhesion, and motility." (PMID 22385615, 2012).
megakaryoblastic leukemia (1 paper, 2021). "The dominant component of this model correlated with αSMA−PDGFRα+ fibroblast‐like cell content (p = 2.4E‐05) and Arg1+ macrophage content (p = 2.2E‐04) and was driven by serum response factor (SRF), possibly in a megakaryoblastic leukemia‐1/2 (MKL1/2) dependent manner." (PMID 34185408, 2021).
metastatic cancer (1 paper, 2022). A carcinoma which has spread from the original site of growth to another anatomic site. "Ultimately, both tumor cell-intrinsic and extrinsic signals may shape the acquisition of MetRes features in brain metastatic cancer cells via RhoA and SRF." (PMID 36509758, 2022).
microcephaly (1 paper, 2014). A congenital or acquired developmental disorder in which the circumference of the head is smaller than normal for the person's age and sex. "While disruption of the MKL2:SRF axis has been associated with severe microcephaly and disordered brain development in multiple model systems, the role of this transcription factor complex has not been previously demonstrated in human brain development." (PMID 23692340, 2014). "We also sequenced all UTR and coding regions of MKL2 and SRF in 36 additional cases of severe microcephaly from three geographically distinct centers." (PMID 23692340, 2014).
monocytic leukemia (1 paper, 2012). "For example, in response to LPS, ERK1/2-activated Elk-1, along with serum response factor (SRF), bind and activate the Egr1 promoter in THP-1 human monocytic leukemia cells." (PMID 23248776, 2012).
muscle atrophy (1 paper, 2017). The loss of muscle tissue due to inactivity or disease. "Endothelial MRTF/SRF ablation can also lead to incomplete formation of the retinal vasculature in the eye44, and both SRF deletion or treatment with CCG-1423 significantly worsened denervation-induced muscle atrophy in mice." (PMID 28364121, 2017).
Myalgia (1 paper, 2022). "In skeletal muscle cells, this transcription factor was associated with the activation of pro-inflammatory immune response in patients with myalgia and with MyHC IIB expression, when associated with MEF2 and the serum response factor (SRF)." (PMID 35255809, 2022).
myelofibrosis (1 paper, 2024). A partial or complete replacement of the bone marrow stroma by fibrous tissue. "Furthermore, the identification of vascular defects in the ThPO and MPL models of myelofibrosis raises the possibility that EndMT, increased biological activity of YAP1/TAZ and SRF-mediated changes in gene expression, but also EC cytoskeletal function, might contribute to fibrosis." (PMID 39155965, 2024).
myocardial infarction (1 paper, 2021). Gross necrosis of the myocardium, as a result of interruption of the blood supply to the area, as in coronary thrombosis. "Methods/Results: We used SRF small interfering RNA (siSRF), SRF small hairpin (shSRF) RNA sequence adenovirus, PI3K/Akt/GSK3β pathway inhibitors, t-AUCB, and 14,15-EEZE (a preparation of EETs antagonists) to treat mouse cardiomyocytes overexpressing miR-1 and mice with myocardial infarction (MI)." (PMID 34646152, 2021).
myotonic dystrophy (1 paper, 2017). An inherited progressive disorder affecting the muscles. "Since SRF regulates DMPK in SMC, we hypothesized that alteration of L-type calcium channel expression by DMPK, resembling the regulatory pathway of the myotonic dystrophy model, is responsible for the functional changes of Srf KO SMC." (PMID 28152551, 2017).
oral squamous cell carcinoma (1 paper, 2023). "Serum response factor (SRF) regulates pro-carcinogenic genes in various cancers, but its role in oral squamous cell carcinoma (OSCC) remains unclear." (PMID 36831659, 2023).
osteoarthritis (1 paper, 2023). A noninflammatory degenerative joint disease occurring chiefly in older persons, characterized by degeneration of the articular cartilage, hypertrophy of bone at the margins and changes in the synovial membrane. "There was a significant interaction between time and osteoarthritis for CRE, NFkB, SRE, SRF with a trend for osteoarthritis synovial fluid-derived EVs at later time points to have a more pronounced effect." (PMID 37834337, 2023).
pemphigus (1 paper, 2023). Pemphigus is a group of rare autoimmune diseases that cause blistering of the skin and mucous membranes (mouth, nose, throat, eyes, and genitals).This conditioncan occur at any age, but often strikes people in middle or older age. "Previous work by others has found that activation of RhoA, a canonical upstream activator of MRTF and SRF, can prevent keratinocyte dissociation induced by pemphigus antibodies in vitro." (PMID 37471166, 2023).
Peptic ulcer (1 paper, 2011). The term peptic ulcer refers to acid peptic injury of the digestive tract, resulting in mucosal break reaching the submucosa. "Serum Response Factor (SRF), a transcription factor protein, binds to serum response elements to control particular genes expressions for peptic ulcer healing." (PMID 21410985, 2011).
periodontitis (1 paper, 2022). An acute or chronic inflammatory process that affects the tissues that surround and support the teeth. "Furthermore, 12 hub genes ranked by the top 10% genes with high degree connectivity and five TFs, including SRF, CNOT4, SIX6, SRRM3, NELFA, and ONECUT3, were identified and might play crucial roles in the molecular pathogenesis of periodontitis." (PMID 35397550, 2022).
primary immunodeficiencies (1 paper, 2021). "Here, we review what is known about MKL1 deficiency and other MKL/SRF (serum response factor)-related actin-based primary immunodeficiencies." (PMID 33692789, 2021). "In conclusion, analysis of primary immunodeficiencies involving MKL/SRF targets and putative targets implicate ARP-subunits as possible targets downstream of MKL/SRF that could be involved in regulating leukocyte adhesion and migration in vivo." (PMID 33692789, 2021).
pulmonary lymphangioleiomyomatosis (1 paper, 2023). "Interestingly, a role for SRF in controlling MMP gene expression has previously been proposed in the context of megakaryocyte migration and tissue damage in pulmonary lymphangioleiomyomatosis." (PMID 37266453, 2023).
Sepsis (1 paper, 2025). Sepsis is defined as life-threatening organ dysfunction caused by a dysregulated host response to infection. "In sepsis-associated acute lung injury, transcription of Myosin Light Chain Kinase mediated by the serum response factor (SRF) can prevent ferroptosis in polymorphonuclear neutrophils." (PMID 41326356, 2025).
serous ovarian cancer (1 paper, 2019). "In contrast to the small gene set (IGF2BP1, SRF, FOXK1 and PDLIM7), the enlarged gene set (35 genes plus IGF2BP1 and SRF) was significantly associated with poor OS probability in serous ovarian cancer, HCC as well as LUAD, as supported by HR values ranging from 1.52 to 2.15." (PMID 30371874, 2019).
Skeletal muscle atrophy (1 paper, 2021). The presence of skeletal muscular atrophy (which is also known as amyotrophy). "Emerging evidence also suggests that the disruption of positive regulators of muscle hypertrophy (serum response factor and myocardin-related transcription factor A) may result in the development of skeletal muscle atrophy with age." (PMID 33970954, 2021).
soft-tissue tumor (1 paper, 2022). "Translocation events involving the SRF gene have been described in literature for different types of soft tissue tumors." (PMID 36421692, 2022). "Lastly, SRF::STAT6 fusion was reported in a case of deep soft-tissue tumor of the arm in a 15-year-old boy, expressing a full smooth-muscle phenotype and overlapping features with the SRF::RELA myofibromas." (PMID 36421692, 2022). "Here we investigated SRF rearrangements in soft tissue tumors, along with a gene expression profile analysis to gain insight into the oncogenic mechanism driven by SRF fusion." (PMID 36421692, 2022). "The recognition of the specific gene signature driven by SRF rearrangement in soft tissue tumors could aid the molecular classification of this rare tumor entity and support therapeutic decisions." (PMID 36421692, 2022).
status epilepticus (1 paper, 2016). Status epilepticus is defined as a continuous seizure lasting more than 30 min, or two or more seizures without full recovery of consciousness between any of them. "To identify direct targets of SRF bound in vivo to the gene promoters in the hippocampus, we applied a model of kainic acid-induced status epilepticus." (PMID 25636686, 2016). "Interestingly, the increased binding of SRF to DNA and upregulation of SRF protein levels were found in the hippocampus after pilocarpine-induced status epilepticus, and SRF accumulation and phosphorylation were observed after kainic acid-induced status epilepticus." (PMID 25636686, 2016). "The lack of downregulation of Cacna1h mRNA after status epilepticus in SRF KO mice may contribute to their enhanced epileptic phenotype." (PMID 25636686, 2016).
T-cell lymphoma (1 paper, 2012). "Thus, MRTF:SRF activation by Tip, a viral oncoprotein essential for the development of fulminant T-cell lymphoma characterized by infiltration of multiple organs, may well contribute to viral oncogenesis and tissue invasion of tumor cells." (PMID 22385615, 2012).
teratocarcinoma (1 paper, 2022). A germ cell tumor characterized by the presence of an embryonal carcinoma component and a teratoma component. "Although HHEX functions as a transcriptional coactivator for SRF in fibroblasts and inhibits Jun-mediated gene activation in teratocarcinoma, it is likely that HHEX coordinates with SRF and AP1 to positively regulate YAP/TEAD activity in CRC." (PMID 36008411, 2022).
thyroid cancer (1 paper, 2015). "Moreover, in vitro assays have indicated that overexpression of SRF in thyroid cancer cells enhances the expression level of c-Fos protein, cell migration, and invasiveness." (PMID 25753578, 2015).
triple-negative breast carcinoma (1 paper, 2021). An invasive breast carcinoma which is negative for expression of estrogen receptor (ER), progesterone receptor (PR), and human epidermal growth factor receptor 2 (HER2). "In triple-negative breast cancer cells, the authors identified the pathway mediated by miR-206: it targets TWF1, megakaryoblastic leukaemia (translocation) 1 (MKL1), and serum response factor (SRF), and subsequently leads to lower levels of IL-11 mRNA and protein expression." (PMID 34201209, 2021).
uterine tumors (1 paper, 2022). "In addition, the histopathological and molecular features of three uterine tumors carrying SRF::RELA fusions were recently identified and compared to SRF::RELA-positive perivascular myoid tumors arising in other anatomical districts." (PMID 36421692, 2022).
visceral myopathy (1 paper, 2023). "Itga8 is preferentially expressed in vascular over visceral SMCs, and the Itga8-Cre model evaded a severe visceral myopathy when used to delete serum response factor (SRF)." (PMID 37561588, 2023).
tumor (120 papers, 2009 to 2026). "This suggested that the IGF2BP1-dependent enhancement of SRF expression is associated with the recently reported role of IGF2BP1 in promoting tumor growth and metastasis." (PMID 30371874, 2019). "The anti-tumor effects of SRF were shown to be associated with the microtubule depolymerization and apoptosis induction." (PMID 25354194, 2014). "SRF expression in the tumor cells was associated with poor differentiation, deep invasion and lymph node metastasis (P<0.05)." (PMID 23426188, 2013). "Abundant SRF expressed in OSCC tissues was closely associated with tumor metastasis." (PMID 36831659, 2023). "The identification of the specific gene signature driven by SRF fusion could aid the molecular diagnostic process and guide the therapeutic decisions with respect to the clinical behavior of this rare tumor entity." (PMID 36421692, 2022). "Interestingly, SRF has also been linked to tumor invasion, proliferation, metastasis and resistance to therapy in different cancer types." (PMID 30621209, 2019). "In addition, our expression analyses showed that, among potential Mir34a targets, genes associated with the induction of STAT3, JUN and SRF expression signatures are presumably involved in the opposing regulation of intestinal homeostasis and tumor formation by Mir34a and Csf1r signaling." (PMID 36147476, 2022). "miR-200c inhibits tumor metastasis by downregulating the expression of the transcription factor c-Jun and MRTF/SRF, which in turn interferes with the expression of the cytoskeletal protein filamin A, thereby reducing the motility of tumor cells." (PMID 39859424, 2025). "Some small molecule compounds that can induce tumor cell ferroptosis such as SRF and SAS have been used in clinical studies." (PMID 40994946, 2025). "Recent evidence further suggests cooperation with activator protein 1 (AP‐1), myocardin‐related transcription factor (MRTF), and serum response factor (SRF), reinforcing their role in driving fibroblast activation and tumor progression." (PMID 40686923, 2025). "The co-delivery of SRF and anti-miRNA27a showed a marked increase in the proportion of apoptosis tumor cells than that of free SRF." (PMID 38831883, 2024). "SRF can be selectively deployed to induce apoptosis in tumour cells located within the normoxic zone." (PMID 39276361, 2024). "Phosphatase and tensin homolog (PTEN), a multifunctional tumor suppressor, also functions as an essential co-factor of SRF that activates SRF-dependent VSMC differentiation gene transcription." (PMID 38279051, 2024). "In tumor tissue, nanoparticles 54b&SRF@BSA decreased the level of HIF-1α protein ( ~ 25% relative to the control) after irradiation via inhibition of mitochondrial respiration and normalization of the tumor vasculature." (PMID 39138299, 2024). "SRF expression has been proved to drive the hepatocarcinogenesis 35, tumor aggressiveness 36, and sorafenib resistance 37 and YY1 induced cell proliferation 38 and tumor angiogenesis 39 in HCC." (PMID 39247819, 2024). "SRF, a small chemical kinase inhibitor, suppresses the growth of tumor cell and neovascularization by inhibiting the RAF/MEK/ERK signal path." (PMID 39276361, 2024). "Targeting MYOCD/SRF interaction with a specific inhibitor decreased the viability of a cell line derived from this tumor subgroup, which makes this pathway a potential therapeutic target." (PMID 36672483, 2023). "Clinical data confirmed that elevated SRF expression is positively correlated with a more aggressive tumor phenotype and lymph node metastasis." (PMID 36831659, 2023). "Scholars have proven that IGF2BP1 can upregulate serum response factor (SRF) expression by a m6A-mediated decrease in mRNA decay, thereby enhancing tumor cell proliferation and invasion." (PMID 37304234, 2023).